FOXP3 (forkhead box P3)
Diseases named in the same sentence as FOXP3 in open-access papers (continued):
Sharing a sentence is not in itself a finding about the gene and the disease.
infection (continued). "Second, an increase in the frequency of FoxP3+ Tregs was detected in the blood and in the lymph nodes after infection of both species, with an earlier and more dramatic increase in AGMs that correlated with limited or resolved systemic inflammation and immune activation." (PMID 19214220, 2009). "Interestingly, Foxp3+CD25+CD4+ regulatory T cells are highly enriched following infection, both in the periphery and in the brain, where the virus intensively replicates." (PMID 19319188, 2009). "Importantly, using microbiota-targeted treatment methods, we prove that this signaling bolsters gut microbiota-mediated host intestinal Foxp3+ Treg cell expansion and parasite survival and that therapies targeting this signaling are effective in treating infection." (PMID 40266093, 2025). "Intraperitoneal injection of 5,000 trypomastigotes (Tulahuen strain) in Foxp3 reporter mice induces a mortality rate of approximately 50%, occurring within a narrow window during the acute phase of infection, typically between 20–22 and 35–38 days post infection (dpi)." (PMID 39883714, 2025). "At 3 h post infection the FoxP3+level was 87%, p < 0.0086 which decreased significantly at 6 h (67%, p < 0.0003), 12 h (57%, p < 0.0001) and finally decreased to the level 40% (p < 0.0001) at 24 h post infection when compared to the level expressed at 0 h post JEV infection." (PMID 36707891, 2023). "The expression and activity of IDO1 during infection were maintained stably greater at night than during the day in CF mice, as well as levels of Foxp3, Il10 and Tgfb gene expression, which may explain the reduced inflammatory damage and PMN recruitment in mice infected at ZT12." (PMID 36896128, 2023). "In the first week after infection, FoxP3 expression is lower while T-bet expression is higher on activated CD4+ T cells in μMT mice; however, we found expression of FoxP3 and T-bet was similar in activated CD4+ T cells from B cell MHCII deficient mice and control animals one week post-infection." (PMID 37721965, 2023). "Furthermore, reduced CD25 expression in aged FOXP3+ cells and their impaired ability to compete for IL-2 may also contribute to Treg dysfunction and immunopathology during infection in the elderly." (PMID 35821823, 2022). "Five days post secondary infection, CD25 were slightly upregulated while Foxp3 was downregulated in the lung tissue resident Treg cells, which are both adjusted back to a level comparable to that observed right before the secondary infection, by 19 days post infection." (PMID 36159872, 2022). "In addition to FoxP3, Myeloid Derived Suppressor Cells (MDSCs) may be responsible for ferrets’ inability to control infection." (PMID 36051240, 2022). "No obvious change or reduction in Tfr (CXCR5+PD1+CD4+FOXP3+) cells.Tfr cells may limit the immune effect caused by a persistent antigen or infection." (PMID 36389806, 2022). "However, the ability of multiple cDC subsets to induce FOXP3 may be problematic for responses to infection or injury." (PMID 33533717, 2021). "Similarly, in a study with mice infected with L. infantum, a high frequency of CD4+CD25+ T cells expressing FoxP3 was found in the lymph nodes in the first weeks of infection, followed by a decrease in the subsequent chronic phase of the disease, supporting the observed results in the present study." (PMID 32760744, 2020). "Although we noted a general increase of Foxp3+ Treg numbers in infected mice when compared to naïve mice throughout the study period, a transient but significant increase of the proportion of Tregs was uniquely detectable at 7 days post-infection within the peritoneal exudates of mice." (PMID 32457746, 2020). "Furthermore, the expansion of CD4+ FoxP3+ T cells in lymphoid organs of mice with chronic T. canis infection, along with the higher levels of IL-10 in spleen and sera, support their role in the host systemic regulatory response to the infection." (PMID 32268573, 2020).
infection (continued). "While it is now acknowledged that CD4+ T cells expressing CD25 and Foxp3 (Treg cells) regulate immune responses and, consequently, influence the pathogenesis of infectious diseases, the regulatory response mediated by Treg cells upon infection by Trypanosoma cruzi was still poorly characterized." (PMID 30455700, 2018). "The associations between TNFα mRNA (P = 0.03) and subsequent infection were independent of the duration of the operation whereas the associations between IL-23 (P = 0.44), RORγt (P = 0.43), FOXP3 (P = 0.49), IL-12 (P = 0.60) and T bet (P = 0.11) mRNA and subsequent infection were not." (PMID 30212506, 2018). "Thus, we identified whether populations of CD4+ T cells and Foxp3+ Tregs within the TC and mLN altered upon infection according to the applied gating strategy (Online Resource 4)." (PMID 29931394, 2018). "Besides a considerable expansion of CD4+ Foxp3+ Tregs in the mLN of infected mice, most prominent by day 10 post infection, we also detected increased frequencies of Tregs in the LP during the course of infection." (PMID 28938014, 2017). "After secondary infection of Il4rafl/fl mice, the proportion and absolute number of ex-Foxp3 Th2 cells were significantly reduced compared with Hp 2° Il4rawt/wt mice, demonstrating a fundamental requirement for IL-4 signaling in Foxp3-expressing cells for the development of ex-Foxp3 Th2 cells." (PMID 28507062, 2017). "Indeed, after a primary infection with the natural mouse parasite Heligmosomoides polygyrus, the early expansion and activation of Foxp3-expressing T reg cells limits excessive T helper 2 cell (Th2 cell) responses and immunopathology, resulting in the establishment of chronic infections." (PMID 28507062, 2017). "However, Tregs only accounted for approximately 10% of the total IL-10+CD4+ T cells in the uninfected mice and slightly more than 15% of the total IL-10+CD4+ T cells in the infected mice, congruous with an infection-dependent increase in IL-10 production by Foxp3+CD4+ T cells." (PMID 28710387, 2017). "We previously demonstrated that acute murine T. cruzi infection results in an impaired peripheral CD4+Foxp3+ T cell differentiation due to the acquisition of an abnormal Th1-like phenotype and altered functional features, negatively impacting on the course of infection." (PMID 26745276, 2016). "Therefore, STAT5 and CD25 expression could be controlled by DNA methylation as occurs with Foxp3, thus explaining their downregulation upon infection." (PMID 27242797, 2016). "Also, the fact that CD4+Foxp3+ Tregs can regulate the progression of WNV encephalitis in an infection model using depletion of CD4+Foxp3+ Treg cells suggests an important role for CD4+Foxp3+ Tregs in regulating the progression of fatal neuroinflammation caused by flaviviruses." (PMID 27439902, 2016). "We hypothesized that larval S. mansoni parasites rapidly co-opt Foxp3+ Treg cell function at an early stage of infection to benefit their own survival, inducing the activation and expansion of Foxp3+ Treg cells during the period when the larvae are most vulnerable to immune attack." (PMID 26195548, 2015). "Hence, we investigated whether S. mansoni parasites would also induce Foxp3+ Treg cell expansion during the early stages of infection when the parasites transit the lungs." (PMID 26195548, 2015). "Moreover, we detected a slight induction of FoxP3+ Tregs in the MLN as the infection progressed." (PMID 25942314, 2015). "Also, the proportion of CD4+CD25+Foxp3+ T cells among splenocyte population was highly elevated in recipients treated with ES L1 primed DCs similarly to the expansion of these cells during the muscle stage of the infection." (PMID 26114122, 2015). "Additionally, to directly assess whether reduced Foxp3+ Treg numbers Itgb8 (CD11c-Cre) mice was responsible for protection from infection, we rescued Treg numbers by adoptively transferred Foxp3+ Tregs from GFP-Foxp3 mice prior to infection." (PMID 24098124, 2013).
infection (continued). "In addition, infection corresponds to reduced placental expression of FoxP3 at early pregnancy, indicating that infection may diminish the number or function of Tregs in these tissues." (PMID 23870389, 2013). "Impaired lamina propria Foxp3+ Treg-cell responses were associated with increased production of IL-4 and IL-13 by CD4+ T cells, demonstrating that ICOS dominantly downregulates Type 2 responses at the infection site, sharply contrasting with its Type 2-promoting effects within lymphoid tissue." (PMID 23319295, 2013). "Moreover, the locally induced infection with WT or attenuated form of L. major directly confirms that the magnitude of pathogen-induced inflammation is a critical factor in the emergence of TEFF cells from Foxp3+ TREG cell population." (PMID 22545118, 2012). "However, the number of Foxp3-positive cells in the liver, spleen, lymph node or thymus was not significantly different between PD-1-deficient mice and their WT littermates after 72 h of MHV-3 infection." (PMID 21750671, 2011). "The frequencies of T CD4+CD25+Foxp3+ and CD4+LAP+ cells were investigated by flow cytometry in draining lymph nodes weekly during the infection." (PMID 40745935, 2026). "The number of activated T cells (subset 2) increased substantially after infection with upregulation of the IFNG, STAT3, STAT4, IL9, FOXP3, and TGFBR1, TGFBR2 genes." (PMID 40573402, 2025). "This is in contrast to the immune‐suppressive profile that is present during infection, which includes increased numbers of CD4 + CD25 + FOXP3 + T cells, antigen‐specific hyporesponsiveness, and distortion of the T cell memory pool." (PMID 39560407, 2024). "We found low frequencies of Foxp3+CD4+ Tregs at 8 dpi, which only slightly increased during the course of infection in the bone marrow." (PMID 37427590, 2023). "At 12 h and 144 h post-infection, a higher percentage of CD4+ CD25+ and CD4+ CD25+ Foxp3 cells were observed in the HLA-A11/DR1 Tg group." (PMID 38035330, 2023). "Despite high expression of CCR5 and CXCR4 by tTregs, FoxP3 + CD3highCD8- thymocytes were much less prone to in vitro infection with R5- and X4-tropic HIV strains compared to FoxP3-CD3highCD8- thymocytes." (PMID 37547675, 2023). "Further analysis of CD44+CD4+ T cells in WT animals revealed FoxP3 expression was preferentially enhanced among CXCR5+ populations vs CXCR5- populations (15.40% ±1.93% vs 3.6 ±1.22) at two- and four-weeks post infection." (PMID 37721965, 2023). "During the early acute phase of infection (3 days post-infection), there was a reduction in the frequency and number of CD4+Foxp3+ Tregs in the spleen of CKO mice compared to WT mice." (PMID 37908369, 2023). "Subsequently, FOXP3-overexpressing LN229 and U87MG constructed by lentiviral infection were verified by western blot." (PMID 35401877, 2022). "The depletion of MGL2+ cells conferred mice with partial resistance to the infection and abrogated the increase of CD4+/CD25+ FoxP3+ Tregs induced by the infection." (PMID 36271272, 2022). "We found that they are crucial for infection and differentiation of Tregs, since an increased number of CD4+/FoxP3+CD25+ cells was found in the spleens of infected mice and their depletion abrogated the Treg expansion induced by the infection." (PMID 36271272, 2022). "A strong interaction between dietary APS and NE infection was observed in relation to TLR2, IFN-γ, TNF-α, IL-6, IL-10, RORα and Foxp3 (P < 0.05) in jejunum." (PMID 35265068, 2022). "Although similar frequencies of CTLA‐4+CD4+FoxP3+ regulatory cells (TREG) were found between groups, CTLA‐4 expression in this compartment was twice as high in symptomatic compared to asymptomatic infection." (PMID 35475529, 2022). "The infection leads to the proliferation and differentiation of CD4+CD25+Foxp3+ Tregs via the activation of the TLR2 pathway." (PMID 34222495, 2021).
infection (continued). "In addition to an enhanced CD8+ T cell activation in the periphery during the early infection phase, an altered immune environment at the site of infection, including reduced infiltrations of Foxp3+ Treg and arginase 1+ M2-type cells in DCIR−/− animals at 14 dpi might have influenced TMEV control." (PMID 34893671, 2021). "To determine the overall impact of Tregs on the outcome of CR infection in the presence of IL-33, we next used DEREG mice in our model, which allow the specific depletion of all Foxp3+ Tregs by diphtheria toxin application." (PMID 33654214, 2021). "The proportion of TH2 (CD4+ CD44+ FoxP3- Tbet- GATA3+) cells was significantly lower than the TH1 cells, and ranged from 4% - 11% of the activated CD4+ T-cells in the UgCl223 infection." (PMID 35186781, 2021). "Upon infection, both WT and CD40L-/- mice show an increase in the numbers of CD4+ T cells, CD4+ CD44+ effector CD4+ CD25+ Foxp3+ Tregs compared to their respective MI." (PMID 34898656, 2021). "Nevertheless, it was also demonstrated Pdl1-/- mice infection with L. major induced lower frequencies of a population of CD4+Ly6Chi effector T cells and higher frequencies of Foxp3+ Tregs compared with WT mice." (PMID 33776999, 2021). "FOXP3 and SUB1 were successfully overexpressed in Tcon and Treg cells by infection with recombinant lentivirus." (PMID 34162888, 2021). "The frequency of Tregs (CD4+CD25+FOXP3+) and activated T CD127+ cells (CD4+CD25+FOXP3−CD127hi) in infected mice was determined at different times post-infection in the peritoneum and in important secondary lymphoid organs like lymph nodes and spleen." (PMID 33928043, 2021). "This contrasts with the immune suppressive profile during infection such as antigen specific hypo-responsiveness, T cell memory pool distortion and increased CD4+CD25+FOXP3+T cell numbers." (PMID 33746974, 2021). "The expression of ILT3 increased during infection in C57BL/6 mice and was significantly higher compared to infected BALB/c and F1 mice while the expression remained unchanged by Foxp3− T cells from BALB/c and F1 mice." (PMID 33452272, 2021). "By infection of Foxp3+ T cells, HTLV-1 can evade the immune response by the release of perforin and granzyme from Foxp3 infected T cells." (PMID 32952946, 2020). "In our rhesus macaque model, we found that a proportion of T cells, including Th1/Th2/Th17 cells, displayed a reduction during the middle and late stages of infection, while the CD4+FOXP3+T cell response was activated during this period." (PMID 33180882, 2020). "The frequency of CD4+CD25+FoxP3+ Tregs in peripheral blood and spleen was significantly higher in the rAAV-IL2 treated group than in the control group throughout the infection." (PMID 32111171, 2020). "Furthermore, while the frequency of Foxp3+ expressing regulatory T cells (Tregs) was significantly higher in WT mice after re-challenge, total numbers of these cells were comparable between WT and Icos-/- mice, which was similar to our results from the primary infection." (PMID 32348365, 2020). "After infection with S. mansoni, the percentage of granuloma nTregs (CD4+ CD25+ Foxp3+) has a significant increase at 8 and 16 weeks of the infection." (PMID 32132991, 2020). "Based on these findings, higher infusion of TIL cells and the percentage of CD8+ TIL, less infusion of CD8+PD1+ TIL and CD4+FoxP3+ TIL, and infection with HPV and fever are potential factors predicting the response to TILs and anti-PD1 combination therapy." (PMID 32964058, 2020). "In conclusion, higher infusion of TIL and CD8+ TIL, lower infusion of CD8+PD1+ TIL and CD4+FoxP3+ TIL, and infection with HPV and occurrence of fever are potential factors for predicting the clinical response to combination therapy of TILs and anti-PD1." (PMID 32964058, 2020). "In another study with a similar focus, FoxP3, and TGF-β expression was also found to increase in the lungs with progression of infection, but pro-inflammatory IL-17 increased as well." (PMID 31572365, 2019).
infection (continued). "In the guinea pig model, while studying the pathogenicity of different Beijing sublineages of Mtb, it was shown that highly virulent strains have increasing levels of FoxP3, IL-10, and TGF-β mRNA in lung tissue as infection progresses." (PMID 31572365, 2019). "Although we found the frequencies of CD4+ Foxp3+ Tregs to be comparable in the gastric LP of WT and BATF3-/- mice, both in the steady state and upon infection, the composition of the Treg compartment differed substantially as a result of BATF3 deficiency." (PMID 31188899, 2019). "During the acute phase of infection, brain infiltrating CD25+ FoxP3+ CD4+ T cells were found to express PD-1." (PMID 31105690, 2019). "Whereas, women who cleared their infection post antibiotic treatment, had increased levels of IDO1 and TGF-β1, as well as FoxP3." (PMID 30832593, 2019). "IAV-specific regulatory T cells (Treg, Foxp3+) have been shown to be important in dampening inflammatory signals and proliferation of IAV-specific CD4 and CD8 T cells during infection, thereby preventing excessive damage to host tissues." (PMID 31632414, 2019). "As expected, the frequency of CD3+CD4+Foxp3+ T cells increased in the PLN after 7 and 14 days post-infection." (PMID 31611578, 2019). "On both days 25- and 46-post infection, the frequency of PD1 expressing CD8+ and CD4+Foxp3- T cells were higher in IFNARfl/fl x Foxp3YFP-Cre mice." (PMID 29672594, 2018). "In contrast, Foxp3+ Tregs frequencies and numbers were increased on day 14 post LCMV Armstrong infection in IFNARfl/fl x Foxp3YFP-Cre mice." (PMID 29672594, 2018). "To confirm Treg depletion in these mice, we measured the frequency of Foxp3+cells among CD4+ T cells in MOIL and CLN, on day 1 after re-infection." (PMID 30197637, 2018). "In the present study, spleen cells displayed an increase of IL-10 mRNA at the early stage of infection, but with a delayed increase of Foxp3 mRNA at the middle stage and a decrease of IFN-γ mRNA at the late infection stage." (PMID 30037796, 2018). "Due to the parallel expansion of CD25+Foxp3− cells during infection, this results in a small reduction in the proportion of CD4+CD25+ cells which expresses Foxp3." (PMID 28975357, 2018). "Key Treg molecules FOXP3, CTLA-4, and CD25 were upregulated following infection, alongside an increase in frequency of Tregs with the capacity to home to tissues." (PMID 28815218, 2017). "The present study evaluated the effect of treatment with benznidazole on mRNA expression of IFN-γ, IL-17, IL-10, TGF-β and FoxP3 in spleen and heart tissue of BALB/c mice in the acute phase of an experimental infection with Trypanosoma cruzi, strains JLP or Y." (PMID 29255475, 2017). "At day 4 post infection, HEL-specific CD4+ T cells from sTg-IRBP:HEL mice and nTg controls displayed comparable levels of PD-1 and numbers of HEL-specific CD4+ Foxp3+ Treg were equivalent in these mice." (PMID 29079770, 2017). "Other transgenic mouse models such as Foxp3-diphtheria toxin receptor (DTR) also helped advance our understanding of the function and pathophysiology of Treg especially during ongoing infections and immune activation." (PMID 28421070, 2017). "During infection, 11% of total CD4+ T cells in MLN of B6 mice were GATA3+ while 12% of total CD4+ T cells expressed Foxp3 in infected Irf8-/- mice." (PMID 28968468, 2017). "The results showed that following the infection, the frequency of CD4+ T Foxp3+ cells were reduced in both infected groups at fourth wpi compared with respective naïve littermate control group." (PMID 28775724, 2017). "Intriguingly, the proportion of Foxp3+ cells expressing CD25 increased as a result of infection, mainly after 21 days of infection, coinciding with the minimal IL-2 contents." (PMID 26745276, 2016). "Together, these results indicate a counter-balance between the effects of infection-induced NOTCH1 and SHH signaling cascades to regulate CD4+CD25+FoxP3+ Treg expansion." (PMID 27080341, 2016).